CD70 (CD70 molecule)
Diseases named in the same sentence as CD70 in open-access papers (continued):
Sharing a sentence is not in itself a finding about the gene and the disease.
Adult onset (1 paper, 2021). Onset of disease manifestations in adulthood, defined here as at the age of 16 years or later. "In adult-onset JSLE, hypomethylation of CD70 (encoding for TNFSF7-tumour necrosis factor ligand superfamily member 7) in CD4+ T cells results in increased gene expression and subsequently enhanced B-cell stimulation that contributes to the pathogenesis of SLE." (PMID 33569643, 2021).
central nervous system lymphoma (1 paper, 2020). "In one study of a 67-year-old man with primary central nervous system lymphoma (PCNSL), after a second relapse, it was decided to proceed with chemotherapy with lymphodepletion followed by infusion of fourth generation CD19-CAR and CD70-CAR T-cells (4SCART19 and 4SCART70)." (PMID 33348704, 2020).
chronic GVHD (1 paper, 2024). "We also observed more circulating CD4+CD70+ T cells in patients with chronic GVHD (median onset 210 days after transplant)." (PMID 39028952, 2024).
CMV infection (1 paper, 2022). "Together, our findings show that CMV infection in healthy young and middle-age adults result in reduced proliferation in CMV-specific CD8+ TCM cells due partially to reduced CD70 expression and signaling." (PMID 36368988, 2022).
contact dermatitis (1 paper, 2022). An inflammatory skin condition caused by direct contact between the skin and either an irritating substance or an allergen. "In the same manner, the expression of CD70 was increased in human contact dermatitis, which is a Th1-mediated inflammation." (PMID 35300124, 2022).
endometrial cancer (1 paper, 2023). Primary or metastatic malignant neoplasm involving the endometrium (mucous membrane that lines the endometrial cavity). "In the absence of comprehensive single cell omics data, we calculated the partial correlations between CD70 and CD86 genes with diverse immune cell type fractions based on CIBERSORT analysis of RNA expression profiles of tumors from endometrial cancer patients." (PMID 37106127, 2023).
glomerulonephritis (1 paper, 2025). A renal disorder characterized by damage in the glomeruli. "CD70 has been implicated in promoting inflammatory responses in autoimmune kidney diseases such as lupus nephritis and glomerulonephritis." (PMID 41322097, 2025).
HIV-1 infection (1 paper, 2017). The type species of lentivirus and the etiologic agent of acquired immunodeficiency syndrome (AIDS). "We also showed that during HIV-1 infection, the high frequency of circulating CD4+CD70+ T lymphocytes in HIV-1-infected individuals was associated with increased plasma IgG levels, upregulation of the B cell activation marker CD38 on memory B cells, and proliferation of memory B cells." (PMID 28473831, 2017). "Thus, CD4+CD70+ T lymphocytes appear to have a role in increased B cell activation during HIV-1 infection [reviewed in Ref." (PMID 28473831, 2017).
ischemia (1 paper, 2024). A hypoperfusion of the BLOOD through an organ or tissue caused by a PATHOLOGIC CONSTRICTION or obstruction of its BLOOD VESSELS, or an absence of BLOOD CIRCULATION. "In hindlimb ischemia models, blood flow recovery was compared between CD70−/−, CD80−/−/86−/−, CD70−/−/80−/−/86−/−, and CTLA4+/− mice." (PMID 39926714, 2024).
Kaposi's sarcoma (1 paper, 2019). A malignant neoplasm characterized by a vascular proliferation which usually contains blunt endothelial cells. "CD70 positivity (>10%) was observed in all solid tumour types, with the exception of Kaposi sarcoma (N = 7)." (PMID 31652572, 2019). "Our study demonstrated CD70 expression with varying intensities in all tumour types, excluding Kaposi sarcoma and NKTCL." (PMID 31652572, 2019). "Kaposi sarcoma showed no CD70 expression on the tumour cells." (PMID 31652572, 2019).
kidney tumor (1 paper, 2024). "All CAR-T cells showed specific cytotoxicity against the CD70 positive kidney tumor cell lines (786-O, 769-P, A498, ACHN)." (PMID 38637886, 2024).
leiomyosarcoma (1 paper, 2021). An uncommon, aggressive malignant smooth muscle neoplasm, usually occurring in post-menopausal women. "The antihuman-CD70 mAb vorsetuzumab was conjugated to MMAF towards uterine leiomyosarcoma cell line and its antitumor effects were evaluated in vitro and in vivo." (PMID 34440182, 2021). "CD70 was identified as a specific and highly expressed surface protein in uterine leiomyosarcoma cell lines and in clinical samples of this rare and aggressive gynecologic malignancy." (PMID 34440182, 2021). "This anti-CD70 ADC showed a significant cytotoxicity on SK-LMS-1 cells, displaying IC50 equal to 0.120 nM and it strongly inhibited tumor growth in SK-LMS-1 xenograft mouse models and in uterine leiomyosarcoma PDX mouse models with a relative tumor reduction of 54.5% and 84.7%, respectively." (PMID 34440182, 2021).
liver fibrosis (1 paper, 2016). "The association of other transcripts such as CD70, IFNE and IRF3 with liver fibrosis has been scarcely reported." (PMID 27135246, 2016).
lung neoplasm (1 paper, 2015). A benign or malignant, primary or metastatic neoplasm involving the lungs. "In this study, we report the expression of CD70 on malignant cells of lung neoplasms and the therapeutic benefit of ARGX-110 in CD70+ NSCLC cell lines." (PMID 25951351, 2015).
malignant pleural mesothelioma (1 paper, 2021). A malignant neoplasm that arises from mesothelial cells in the pleura and shows a diffuse growth pattern. "In addition, CD70 expression on malignant pleural mesothelioma and lower CD27–positive TIL accumulation are reported to correlate with poor prognosis." (PMID 35145909, 2021).
MALT lymphoma (1 paper, 2025). An indolent, extranodal type of non-Hodgkin lymphoma composed of small B-lymphocytes (centrocyte-like cells). "Immunofluorescence double staining technique showed the co-expression of CD70 and CD27 in MALT lymphoma samples." (PMID 40078987, 2025).
metastatic tumor (1 paper, 2015). "In the residual four patients with combinations of consecutive tumor specimens, one metastatic tumor (L437, p47) contained CD70-expressing cells, while there were no CD70-expressing cells detectable in the primary tumor (L1046) of the same patient." (PMID 25792975, 2015).
myasthenia gravis (1 paper, 2025). Myasthenia gravis (MG) is a rare, clinically heterogeneous, autoimmune disorder of the neuromuscular junction characterized by fatigable weakness of voluntary muscles. "Increased CD27/CD70 signaling has also been reported in myasthenia gravis (MG) patients." (PMID 40211396, 2025).
mycosis fungoides (1 paper, 2025). Classical mycosis fungoides is the most common type of mycosis fungoides (MF), a form of cutaneous T-cell lymphoma, and is characterized by slow progression from patches to more infiltrated plaques and eventually to tumors. "Twenty‐seven CD70‐positive patients were enrolled, comprising 9, 14, and 4 participants, respectively suffering from Sézary syndrome (SS), mycosis fungoides (MF), and additional subtypes of the disease." (PMID 40629902, 2025).
oncocytomas (1 paper, 2023). "Within tumor samples, CD70 expression was higher in sarcomatoid and clear-cell tumors than in oncocytomas and papillary tumors." (PMID 38139136, 2023).
ovarian tumour (1 paper, 2010). "Our results show that pancreatic and ovarian tumour cell lines, which express high levels of endogenous or transfected CD70, are sensitive to the anti-tumour activity of SGN-75 in vitro and in vivo." (PMID 20664585, 2010).
pancreatic ductal adenocarcinoma (1 paper, 2025). An infiltrating adenocarcinoma that arises from the epithelial cells of the pancreas. "designed CD70‐CAR‐IL‐15 NK cells to target CD70‐positive colorectal and pancreatic ductal adenocarcinoma cells as well as cancer‐associated fibroblasts (CAFs)." (PMID 40629902, 2025).
PFAPA syndrome (1 paper, 2017). An auto inflammatory syndrome characterized by recurrent febrile episodes associated with aphthous stomatitis, pharyngitis and cervical adenitis. "In conclusion, we report an early diagnosed case of CD70 deficiency with an onset of periodic fever, suggesting that in EBV positive patients with signs of PFAPA syndrome molecular analysis of CD70 gene should be performed." (PMID 29434583, 2017).
skin cancer (1 paper, 2025). "This extends prior work connecting UV-induced DNA damage and inflammation to skin cancer and positions CD70 as a direct effector linking these processes." (PMID 41510255, 2025). "Together, our findings reveal a previously unrecognized mechanism linking environmental genotoxic stress to pro-tumorigenic signaling and provide a compelling rationale for developing CD70-targeted strategies for skin cancer prevention and therapy." (PMID 41510255, 2025). "To evaluate the functional significance of CD70 in skin cancer cells, we knocked down CD70 expression by using specific shRNAs in human cSCC cell lines (A431 and SCC12)." (PMID 41510255, 2025). "Targeting CD70 may disrupt this feed-forward inflammatory circuit and provide a therapeutic strategy for inflammation-driven skin cancer." (PMID 41510255, 2025). "Whether CD70 expression extends beyond epithelial cells to modulate fibroblast activation and tumor–stroma crosstalk in UV-induced skin cancer is unknown." (PMID 41510255, 2025).
skin melanomas (1 paper, 2018). "In TCGA-SKCM, all genes (apart from CD70) exhibited significantly higher levels in metastatic skin melanomas compared to primary tumors." (PMID 29515971, 2018).
squamous cell carcinoma (1 paper, 2015). A carcinoma arising from squamous epithelial cells. "Moreover, we have demonstrated particular CD70 expression in stage T4 NSCLC (40% of cases) as well as in squamous cell carcinoma (27% of cases)." (PMID 25951351, 2015).
uterine cancer (1 paper, 2024). Primary or metastatic malignant neoplasm involving the uterine corpus and/or the cervix. "Analysis of the GENT2 database, using expression profiles from the U133_Plus_2.0 microarray platform (GPL570), showed significant upregulation of CD70 in breast, colon, head and neck, kidney, lung, oral, ovary, spleen, thyroid, and uterine cancers compared to adjacent normal tissues." (PMID 39446784, 2024).
tumor (322 papers, 2004 to 2026). "While tumor-specific antigens (TSAs) are ideal targets, their rarity necessitates reliance on tumor-associated antigens (TAAs) like CD70, which is overexpressed in malignancies but transiently in activated lymphocytes." (PMID 40896423, 2025). "High CD70 expression is associated with poor prognosis in several cancer types, further highlighting its role in tumor pathogenesis." (PMID 40597436, 2025). "In conclusion, CD70 represents a compelling molecular target with potential for integrated diagnostic and therapeutic applications across multiple tumour types." (PMID 40629902, 2025). "High CD70 expression, detected predominantly within tumor cells and macrophages, was linked to significantly reduced OS, also when including only early-stage or immune-oasis tumors." (PMID 40205178, 2025). "linked CD70 to immunosuppression and augmented anti-tumor responses by engineering IL-8 receptor (CXCR1/CXCR2)-modified anti-CD70 CAR-T, leveraging radiation-induced IL-8 release to enhance tumor trafficking." (PMID 40896423, 2025). "Aberrant expression of CD70 was linked to tumor progression and immunosuppression in the tumor microenvironment, and it can facilitate immune evasion through interacting with receptor CD2728." (PMID 38589454, 2024). "In this respect, the development of Tregs and increased Tregs activity in the TME are linked to CD27 agonism by CD70+ tumor cells." (PMID 37545491, 2023). "CD70 is also implicated in tumor cell and regulatory T cell survival through interaction with its ligand, CD27." (PMID 36588677, 2022). "Cluster of differentiation-70 (CD70) is a protein implicated in tumor cell survival that also activates regulatory T cells and skews T cells toward exhaustion." (PMID 36572780, 2022). "Taken together, in a majority of the cases, the identified CD70 genetic alterations from DLBCL samples resulted in a loss/reduction of CD70 protein expression in the tumour cells and/or loss of function (CD27 binding)." (PMID 36471481, 2022). "In cancer, HIF-2α enhances CD70 expression, which mediates tumor progression and aggressiveness and is associated with poor prognosis." (PMID 35216458, 2022). "In this study, we construct a tandem CAR molecule targeting 2 tumor-associated antigens, B7-H3 and CD70, and found that TanCAR-T cells distinctly recognize the antigens and exhibited superior antitumor effect when encountering both antigens simultaneously." (PMID 32685008, 2020). "CD70 expression has been reported in some solid cancers and implicated in tumor escape from immunosurveillance." (PMID 25792975, 2015). "Constitutive CD70 expression on tumors or DCs improved antitumor immunity in murine lymphoma models, enhancing NK-mediated rejection of class-1 deficient tumor cells via perforin- and IFN-γ-dependent mechanisms." (PMID 24855562, 2014). "Although CD70 is normally restricted in expression, its upregulation on activated immune cells may theoretically pose a risk of on‐target, off‐tumour toxicity during therapeutic targeting." (PMID 40629902, 2025). "PMBC-derived cells had malignant clones expectedly exhibiting a dominant clonotype (TRBV7-2 and TRAAV2), copy number variations, decreased expression of CD7, and aberrantly elevated expression of KIR3DL2 (CD158k) and CD70, which are known to be tumor-associated." (PMID 40941016, 2025). "Given its close association with tumour immune regulation, CD70‐targeted therapies not only enable direct elimination of CD70‐positive tumour cells but also hold potential to activate effector immune responses and remodel the immunosuppressive microenvironment." (PMID 40629902, 2025). "Interestingly, gene set enrichment analysis in CRC and PDAC patients indicated that CD70 expression was also associated with CAFs residing in the tumor stroma." (PMID 38331849, 2024). "Consequently, the expression of CD70 on tumor cells has also been linked to worse prognosis in several malignancies." (PMID 38331849, 2024).
tumor (continued). "Growing evidence suggests that tumor-associated CD70 expression may have immune suppressive properties." (PMID 38637886, 2024). "Conversely, diminished CD70 expression could be associated with suppressed immune function, contributing to tumour progression." (PMID 39031800, 2024). "The purpose of such a design is to minimize tumor escape mediated by some CD70 epitope loss." (PMID 36932256, 2023). "The expression of CD70 on cancer cells is linked to the induction of regulatory T cells, which may inhibit the immune system in the tumor microenvironment." (PMID 37849799, 2023). "Therefore, lipid depletion also resulted in the incapability of CD70-CD27 interaction in regulating Treg immunosuppression in the NPC-PBMC co-culture system, causing elevated anti-tumor immunity in both CD70-NC and CD70-KO groups." (PMID 37024479, 2023). "We thus first integrated the data from the Chinese DLBCL cohort, which includes WGS and WES data from 96 pairs of tumour/control samples and targeted sequencing data from 204 tumour‐only samples, to identify somatically occurring (tumour‐specific) mutations in CD70." (PMID 36471481, 2022). "So far, the exact underlying mechanisms of CD70+ tumor cells remains largely unknown, although several studies suggest that epigenetic alterations regulate CD70 expression." (PMID 34991665, 2022). "Thus, we chose two tumor-associated antigens, B7-H3 and CD70, as the targets for CAR-T therapy in our study." (PMID 32685008, 2020). "The loss of either CD70 or HIF-2α considerably weakened tumor growth, suggesting that both markers could be potential candidates for GBM therapy." (PMID 32429463, 2020). "CD70 overexpression on tumour cells is associated with poor prognosis." (PMID 31652572, 2019). "Consistently, AlloCAR70-NKT cells also exhibited robust cytotoxicity against CD70-knockout RCC tumor cells, including 786-O-FG engineered by CRISPR/Cas9, further supporting that their antitumor activity is partially mediated through NKR-dependent mechanisms." (PMID 41533507, 2026). "In vivo and in vitro models reveal that fibroblast CD70 supports tumor growth and establishes a pro-tumorigenic TME." (PMID 41510255, 2025). "Treatment with either conventional CAR70-T cells or AlloCAR70-NKT cells suppressed tumor growth and prolonged mouse survival in the CD70-expressing model of PDX#22 and 786-O-FG, with AlloCAR70-NKT cells demonstrating superior antitumor efficacy." (PMID 40885188, 2025). "The in vitro potency of CD70 TRuC T cells was assessed by measuring their tumor lytic activity and inflammatory IL-2 and interferon-gamma (IFN-γ) cytokine release response to CD70+ tumors." (PMID 40519930, 2025). "Tumors derived from CD70-silenced cells exhibited significantly reduced tumor size (representative images), weight, and volume compared with controls but had no significant overall effect on body weight." (PMID 41510255, 2025). "CD70 chimeric antigen receptor natural killer cells (CD70-CAR-NK), engineered with IL-15, hnCD16, and CD70 knockout, target tumor cells and cancer-associated fibroblasts with minimal off-tumor effects, exhibiting potent cytotoxicity and prolonged persistence." (PMID 40896423, 2025). "Despite these advances, recent studies have revealed that CD70 is aberrantly expressed not only in tumour cells but also in specific stromal components within the tumour microenvironment." (PMID 40629902, 2025). "In conclusion, we identify CD70 as a central integrator of DNA damage, inflammatory signaling, and tumor–stroma interactions in UV-driven NMSC." (PMID 41510255, 2025). "ADP-520 showed low basal activation while retaining selective on-target cytotoxicity against CD70+ tumors in vitro and avoiding on-target/off-tumor fratricide against activated T lymphocytes." (PMID 40519930, 2025). "Strikingly, AlloCAR70-NKT cells were capable of killing both CD70+ and CD70− tumor cells, with enhanced efficacy toward CD70+ targets, indicating both CAR-dependent and CAR-independent mechanisms." (PMID 40885188, 2025).